THY1 (Thy-1 cell surface antigen)
Diseases named in the same sentence as THY1 in open-access papers (continued):
Sharing a sentence is not in itself a finding about the gene and the disease.
ovarian carcinoma (32 papers, 2014 to 2025). A malignant neoplasm originating from the surface ovarian epithelium. "assessed the expression of THY1 and EpCAM on a number of primary ovarian cancer patient-derived samples using high-content imaging." (PMID 38146364, 2023). "The latest findings report that in several tumors, including ovarian cancer, THY1 is overexpressed in cancer stem cells (CSC) and the tumor microenvironment, enhancing proliferation and metastasis abilities." (PMID 35172861, 2022). "On the one hand, Thy-1+/+ cancer stem cells in ovarian cancer show a high proliferative and self-renewal capability compared to Thy-1−/− cells." (PMID 35733855, 2022). "With MICS we analysed human glioblastoma, ovarian and pancreatic carcinoma, and 16 healthy tissues, identifying the pair EPCAM/THY1 as a potential target for chimeric antigen receptor (CAR) T cell therapy for ovarian carcinoma." (PMID 35115587, 2022). "In ovarian cancer cells, the scenario is more complex since Thy-1 can exert both tumor promoter and suppressor functions." (PMID 35733855, 2022). "We were additionally able to validate these findings by identifying poorer clinical outcomes for women with ovarian cancer and high expression of Thy-1." (PMID 31735168, 2019). "Serous ovarian cancers with high Thy-1 expression have poorer outcomes (median PFS 15.8 vs. 18.3 months, P = 0 < 0.001; median OS 40.1 v." (PMID 31735168, 2019). "We then demonstrated 12-fold higher expression of Thy-1 at the RNA level in GFP+ A2780 ovarian cancer cells compared to GFP- A2780 cells." (PMID 31735168, 2019). "In summary, we identified Thy-1 as a surface marker of CSCs in ovarian cancer and further demonstrated increased proliferative and self-renewal capability in Thy-1 expressing cells that was reversible with Thy-1 knockdown." (PMID 31735168, 2019). "Using available data from the Schwartz ovarian dataset, we identified highest expression of Thy-1 in serous and endometrioid histologic subtypes of ovarian cancer." (PMID 31735168, 2019). "Our primary aim was to validate Thy-1 (CD90) as a cancer stem cell (CSC) marker in epithelial ovarian cancer (EOC), correlate with clinical outcomes, and assess as a potential therapeutic target." (PMID 31735168, 2019). "We were able to demonstrate decreased proliferation and self-renewal after Thy-1 knockdown in ovarian cancer cells, suggesting a potential for targeting." (PMID 31735168, 2019). "We identified significantly higher expression of Thy-1 in ovarian carcinoma compared to benign ovarian epithelium." (PMID 31735168, 2019). "Nevertheless, THY1 played an opposite role in ovarian cancer." (PMID 38819947, 2024). "Our high-throughput screen suggested Thy-1 as a putative CSC marker in ovarian cancer." (PMID 31735168, 2019). "Since we had noted that Thy-1 expression was higher in ovarian CSCs, we hypothesized that Thy-1 may act as a surrogate marker for stem cell populations in women with ovarian cancer and therefore may be a relevant indicator of prognosis." (PMID 31735168, 2019). "Interestingly these authors have also indicated that Thy-1/CD90-β3 integrin interaction inhibits ovarian cancer formation and in this case, CD133 decreases its expression in cancer stem cells, while the phosphorylation of AMPK increases." (PMID 31428610, 2019). "Investigation of the role of Thy-1 in ovarian cancer is limited." (PMID 31735168, 2019). "Elevated THY1 significantly correlated with poor overall survival (OS) in glioblastoma multiforme, kidney renal papillary cell carcinoma, LUSC, mesothelioma, ovarian cancer, skin cutaneous melanoma, and uveal melanoma." (PMID 38819947, 2024). "Our previous study showed that the commercially available ovarian cancer cell lines ES-2 and OAW-42 expressed the markers characteristic for the mesenchymal stem cell markers CD73 (ecto-5′-nucleotidase), CD90 (Thy-1), and CD105 (endoglin)." (PMID 38791431, 2024).
ovarian carcinoma (continued). "To test one of the identified candidate pairs, we generated ovarian cancer cells co-expressing EPCAM and THY1 in combination with eGFP." (PMID 35115587, 2022). "A2780 ovarian cancer cells were sorted using Fluorescence Activated Cell Sorting (FACS) and Thy-1 high cells demonstrated both higher proliferative capability as well as higher self-renewal on limiting dilution assay." (PMID 31735168, 2019). "Intriguingly, the effect of Thy-1/CD90 presence is opposite in these cancer types; behaving as a tumor promoter in liver, but as a tumor suppressor in ovarian cancer." (PMID 31428610, 2019). "For THY1 gene, though it was reported as a putative tumor suppressor of ovarian cancer, our study did not produce the same results as previous ones, despite THY1’s presence in our prediction of potential FAP association networks." (PMID 33109151, 2020). "From a total of 242 cell surface proteins that were included in this high-throughput screen, we identified Thy-1 was also more highly expressed in ovarian CSCs as compared to non-CSCs in A2780 cisplatin-naïve ovarian cancer cells." (PMID 31735168, 2019). "THY1 expression is indicative of poor outcomes and is found to be higher in ovarian CSC than in non-CSC and promotes proliferation in ovarian cancer." (PMID 37189618, 2023). "We identified THY1 with a characteristic expression on non-epithelial cells like fibroblasts and co-expression with EPCAM on ovarian cancer cells." (PMID 35115587, 2022). "One of the target pairs consists of THY1 and EPCAM, which were co-expressed on ovarian cancer cells in a subset of HGSOC but not on healthy tissue." (PMID 35115587, 2022).
gastric cancer (29 papers, 2011 to 2025). A primary or metastatic malignant neoplasm involving the stomach. "•THY1 is linked to the epithelial–mesenchymal transition in gastric cancer." (PMID 40476057, 2025). "We investigated the regulation of THY1 expression by its putative transcriptional regulators in gastric cancer cell lines to translate our bioinformatic predictions into experimental evidence." (PMID 40476057, 2025). "While our study provides novel insights into the transcriptional regulation of THY1 in gastric cancer, several limitations should be acknowledged." (PMID 40476057, 2025). "Having established an experimental model of gastric cancer cell lines with high and low THY1 expression, we next aimed to validate the direct regulation of THY1 by its putative transcriptional regulators." (PMID 40476057, 2025). "This enhancer-based regulatory model presents a relevant complementary mechanism for the integration of transcriptomic and epigenomic data to fully elucidate the multilayered regulation of THY1 in gastric cancer." (PMID 40476057, 2025). "We collected gene expression data from 945 gastric cancer samples to delineate the regulatory landscape of gastric cancer and situate THY1 within this context." (PMID 40476057, 2025). "Despite these limitations, our work represents a critical step toward deciphering the transcriptional complexity of THY1, particularly in the context of gastric cancer." (PMID 40476057, 2025). "In this study, we systematically delineated the transcriptional regulatory landscape of THY1 in gastric cancer by identifying six robust putative regulators—PRRX1, TWIST1, SNAI2, MEIS3, VENTX, and EGR2—through an integrative multicohort approach." (PMID 40476057, 2025). "Focusing on the THY1 gene, a known marker of a poor prognosis for patients with gastric cancer, we employed a rigorous multistep refinement process." (PMID 40476057, 2025). "Particularly, THY1 is highly expressed in cancer stem cells of gastric cancer, differentiated acute myeloid leukemia (AML) subtypes, lymph nodes metastasis in esophageal squamous carcinoma cells and also contributes to poor survival in HCC." (PMID 35172861, 2022). "Beside the Lgr5(+)/LGR5-expressing cells, more primitive MSC/MSC-like cells appear to be playing a crucial role in intestinal homeostasis, and MSC-like cells have been isolated from human gastric cancer tissues, marked by high expression of THY1." (PMID 32894084, 2020). "Gastric cancer is a highly heterogeneous disease, and the regulation of THY1 expression may vary depending on the tumor microenvironment or additional epigenetic factors not addressed in this study." (PMID 40476057, 2025). "Additionally, THY1-expressing gastric cancer cells exhibit mesenchymal traits, increased adhesion to the extracellular matrix (ECM), and increased proliferative and migratory potential, facilitating tumor invasion and dissemination." (PMID 40476057, 2025). "Together, these findings provide experimental evidence supporting TWIST1 and SNAI2 as direct regulators of THY1, integrating bioinformatic predictions and experimental insights into a cohesive model of THY1 transcriptional regulation in the context of gastric cancer." (PMID 40476057, 2025). "•TWIST1 and SNAI2 were validated as key regulators of THY1 in gastric cancer." (PMID 40476057, 2025). "In another aspect of THY1 regulation in the context of gastric cancer, recent studies have also proposed complementary hypotheses involving distal regulatory elements." (PMID 40476057, 2025). "Given the robust bioinformatic evidence supporting the regulation of THY1 as a component of an EMT transcriptional program in gastric cancer, we next sought to establish an experimental model to validate the regulation of THY1 by its putative transcriptional regulators." (PMID 40476057, 2025).
gastric cancer (continued). "Similarly, K. Wu and colleagues reported in their work that upregulation of miR-140-5p inhibits the NOTCH signaling pathway and consequently reduces THY1 expression in gastric cancer." (PMID 35172861, 2022). "This study provides experimental evidence of TWIST1 and SNAI2 binding to the THY1 regulatory regions in a gastric cancer cell line with high THY1 expression, supporting the hypothesis that these transcription factors may act as key regulators of THY1 expression in this context." (PMID 40476057, 2025). "We first examined publicly available gene expression data from gastric cancer cell lines to determine whether the heterogeneity of THY1 expression observed in patients’ tumors is also reflected in these in vitro models and to translate the bioinformatic findings into experimental evidence." (PMID 40476057, 2025). "By analyzing the co-expression correlation between CPT1A, IL-8, CXCL5, STC1 and CD44 in stomach cancer tissues through TCGA database, we found that these genes except CXCL5 were positively correlated with CD44 and were positively associated with at least one MSC markers (ENG, THY1, NT5E)." (PMID 37158903, 2023). "However, the precise mechanisms that control THY1 expression in gastric cancer remain unclear." (PMID 40476057, 2025). "A subpopulation of MSCs expressing specific marker genes such as THY1, SPARC, ENG, PRRX1, VCAM1, and MCAM has been identified in primary lesions, ovarian metastases, and peritoneal metastases of gastric cancer." (PMID 40676710, 2025). "Ultimately, our findings enhance the understanding of THY1 as a key player in the EMT and gastric cancer progression, providing a potential biological explanation for its association with a poor prognosis." (PMID 40476057, 2025). "To identify molecular differences between intestinal gastric cancer (IGC) tumors with high and low expression of THY1, we collected data for 180 IGC patients with available RNA-seq data in the TCGA database." (PMID 38254918, 2023). "Despite some controversies, CD44, CD90 (Thy1), and EpCAM (CD326) are thought to enrich gastric cancer stem cells (GCSCs)." (PMID 27107424, 2016). "Taken together, these findings suggest that THY1 is not merely a biomarker of the EMT process but may also be an integral component of the EMT transcriptional program in gastric cancer." (PMID 40476057, 2025).
lung carcinoma (26 papers, 2013 to 2025). "THY has been proven to be a cancer marker, and it has been found that high expression of THY1 is linked to poor prognosis in individuals with extrahepatic cholangiocarcinoma and lung cancer patients." (PMID 34556089, 2021). "THY1 was widely expressed in a variety of malignant tumors (i.e., brain cancer, lung cancer, colon cancer) and normal organs (i.e., brain, kidney, breast)." (PMID 38819947, 2024). "Upregulation of THY1 was reported for lung cancer, and such high expression is negatively correlated with survival time." (PMID 37046850, 2023). "CD90, a cell adhesion molecule, known as thymocyte differentiation antigen-1 (Thy-1), has been reported as a CSC-associated marker for lung cancer." (PMID 35053430, 2022). "Thy-1 is a cell surface glycoprotein, which is closely related to idiopathic pulmonary fibrosis and lung cancer." (PMID 35070996, 2021). "Intriguingly, Thy-1 is also found in malignant tumors, such as liver, esophageal, gastric, gallbladder, and lung cancer, where Thy-1 is likely to act as a tumor promoter." (PMID 33511115, 2020). "We tested the effect of PPS on myofibroblast differentiation on primary HLFs that obtained from adjacent normal lung of a patient with nonsmall cell lung cancer using Thy1+ (eBioscience, San Diego, CA) flow sorting." (PMID 32528292, 2020). "For Thy-1, IHC images also indicated significant over-expression in kidney, and lung carcinoma vessels compared to normal vessels." (PMID 24236063, 2013). "M5 expressed pericyte-associated genes (RGS5, PDGFRB, NES, THY1, KCNJ8) and showed strong similarity to curated pericyte signatures, including pan-cancer C8_RGS5 pericytes, healthy human prostate pericytes and pericytes from lung cancer." (PMID 41378308, 2025). "In lung cancer, miR-1301 acts as an oncogene by inhibiting the Thy-1 and PTRF genes." (PMID 35070996, 2021). "Thy-1 and αSMA were detected in tumor stroma by immunohistochemical analysis of human lung cancers, and quantification of cells that express Thy-1 or αSMA within multiple microscopic fields showed that their levels were positively correlated (P = 0.018, r = 0.665)." (PMID 28744021, 2017). "To determine whether the presence of Thy-1+ CAFs impacts clinical outcome, we sought to probe publicly available lung cancer transcriptomic databases for evidence of Thy-1+ CAF-enrichment." (PMID 28744021, 2017). "Given that mechanosignaling is required for the generation and maintenance of CAFs34, studies are warranted to examine whether Thy-1 drives CAF development in lung cancer." (PMID 28744021, 2017). "Thus, Thy-1 marks a CAF population that adversely impacts clinical outcome in human lung cancer." (PMID 28744021, 2017).
glomerulonephritis (24 papers, 2008 to 2025). A renal disorder characterized by damage in the glomeruli. "A similar improvement in the accumulation of inflammatory cells was observed by stimulating soluble guanylate cyclase and, in turn, enhancing cGMP generation in a rat model of anti-Thy1-induced glomerulonephritis." (PMID 40063586, 2025). "The proinflammatory cytokine IL-17 is upregulated in endothelial cells during the pathogenesis of acute anti-thy1 glomerulonephritis." (PMID 36998608, 2023). "By immunohistochemistry, we observed also a marked upregulation of Nrf2 that was paralleled by enhanced CSE expression in the glomeruli from nephritic rats in a model of anti-Thy-1-induced glomerulonephritis." (PMID 35204708, 2022). "We utilized anti-Thy1 antibody to target CD90 (Thy1) to induce glomerulonephritis in Sprague Dawley rats, and our findings suggest that daily administration of everolimus to anti-Thy1-injected rats reduced markers of renal injury and glomerular damage." (PMID 35008770, 2021). "Our findings suggest that bolus injection of BMDSCs fails to improve glomerular injury whereas everolimus slows the progression of glomerular injury in Anti-Thy-1 induced glomerulonephritis." (PMID 35008770, 2021). "Anti-Thy1 glomerulonephritis was induced in male Sprague Dawley rats by injection of an antibody against Thy1, which is mainly expressed on glomerular mesangial cells." (PMID 35008770, 2021). "The aim of this study was to characterize IL-17 expression over the course of acute anti-thy1 glomerulonephritis, to identify the IL-17 expressing cells, and to elucidate further the IL-17 / TGF-β1 interaction in renal cells." (PMID 27243813, 2016). "The present study analyzes expression of IL-17 in the time course of acute anti-thy1 glomerulonephritis and the role of IL-17 as a potential link between inflammation and fibrosis." (PMID 27243813, 2016). "The pro-inflammatory cytokine IL-17 is up-regulated in endothelial cells during the time course of acute anti-thy1 glomerulonephritis." (PMID 27243813, 2016). "Findings by Border and Noble with overexpression of TGF-β1 in renal fibrosis and successful use of neutralizing anti-TGF-β1 antibody demonstrated that the cytokine TGF-β1 plays as a major role in kidney fibrosis during acute anti-thy1 glomerulonephritis." (PMID 27243813, 2016). "Our study documents a time-dependent expression of the pro-inflammatory cytokine IL-17 in renal endothelial cells in acute anti-thy1 glomerulonephritis." (PMID 27243813, 2016). "Acute anti-thy1 glomerulonephritis in the rat is characterized by an injury phase (6–48 h after induction) with mesangial cell lysis, macrophage influx, and overexpression of proinflammatory cytokines such as TNF-α and IL-1." (PMID 27243813, 2016). "Although p21 expression was returned to the normal level, the increase in FLASH expression in glomeruli was followed at day 12 after induction of Thy-1 glomerulonephritis." (PMID 26208142, 2015). "In fact, FLASH was additionally upregulated 12 days after the induction of Thy-1 glomerulonephritis, such that the expressions of E12 and p21 were returned to their normal levels." (PMID 26208142, 2015). "Imatinib has shown anti-fibrotic effects in different animal models with organ fibrosis, including acute anti-thy1 glomerulonephritis of the rat." (PMID 24119229, 2013). "This view is supported by the renoprotective effects on glomerular mesangioproliferation in acute anti-thy1 induced glomerulonephritis when therapy was started as early as 24 hours after anti-thy1 antibody injection." (PMID 24119229, 2013). "In vivo, PIASy and E12 were dramatically upregulated along with α-SMA and TGF-β in the proliferative phase of Thy1 glomerulonephritis." (PMID 22829926, 2012). "In a model of anti-Thy-1-initiated glomerulonephritis, injections with decorin suppressed the TGF-β activity." (PMID 21494642, 2011).